ERG (ETS transcription factor ERG)
Diseases named in the same sentence as ERG in open-access papers (continued):
Sharing a sentence is not in itself a finding about the gene and the disease.
prostate carcinoma (continued). "A recent study showed that NOTCH factors are direct transcriptional targets of ERG; inhibition of ERG in TMPRSS2-ERG-positive prostate cancer cells and decreased NOTCH1 and NOTCH2 levels." (PMID 31366128, 2019). "Recurrent gene fusions were primarily identified in prostate cancer (TMPRSS2::ERG) and adenoid cystic carcinoma (MYB::NFIB) in 1.74% (9/517) and 1.35% (7/517), respectively in the overall cohort." (PMID 31491926, 2019). "The aberrant activation of the ERG oncogenic pathway due to the TMPRSS2-ERG gene fusion is the major event that contributes to prostate cancer (PCa) development." (PMID 30718921, 2019). "We showed for the first time that ERG transcription factor regulates androgen biosynthesis and subsequent AR activation in prostate cancer cells." (PMID 31638934, 2019). "Fusion of the TMPRSS2 and ERG genes is the most prevalent gene fusion in prostate cancer, occurring in about 50% the cases." (PMID 30664691, 2019). "Structural rearrangements of TMPRSS2-ERG (T2E) are present in over 50% of human prostate cancer and lead to aberrant activation of the ERG transcription factor." (PMID 31013831, 2019). "Similar, the association between the ERG rearrangement and the expression status of ERG in prostate cancer using antibody-based detection has been demonstrated previously in various studies." (PMID 30658688, 2019). "The overexpression of ERG, in a majority of prostate cancers, is driven by this fusion event, which switches ERG to fall under the control of the androgen-driven promotor of the TMPRSS2 gene." (PMID 31275657, 2019). "A study reported that the rearrangement of ERG with SLC45A3 and the loss of SLC45A3 expression were one of the aggressive pathways of prostate cancer progression." (PMID 31228945, 2019). "It has been shown that activation of the TGF-ß signaling pathway is one important consequence of ERG fusion in prostate cancer." (PMID 31452838, 2019). "The TMPRSS2:ERG gene fusion occurs in 40–60% of prostate cancers, and results in deregulation of more than 1,600 genes." (PMID 30899444, 2019). "In this study, we retrospectively examined the relationship between ERG expression and PTEN loss in 119 surgically treated prostate cancer patients from Northeastern Brazil through immunohistochemical analysis." (PMID 31826177, 2019). "In turn, the Wnt signaling pathway is known to be massively up regulated in ERG translocated prostate carcinomas." (PMID 31606028, 2019). "Translocations leading to ERG overexpression are observed in a large group of primary prostate cancer cases and are maintained in CRPC." (PMID 31200487, 2019). "A significant percentage of prostate cancers exhibit a specific gene fusion of the ETS gene ERG and the 5′ region of TMPRSS2 gene." (PMID 31143708, 2019). "In prostate cancer cells, ERG recruits the AR at the level of novel genetic loci and interacts with other transcription factors at the level of AR binding sites, and, through these effects, modifies the transcriptional activity induced by androgen signaling." (PMID 31366128, 2019). "Although fusion of the AR regulated TMPRSS2 promoter to ETS related gene (ERG) that results in ERG overexpression is a common event in CA prostate cancer patients (50–70%), it is less frequent among AA and other ethnic groups." (PMID 31741711, 2019). "Correlative studies in human prostate cancers reveal a frequent association of the TMPRSS2/ERG (TE) fusion gene with loss of PTEN and studies in mouse models reveal that ERG expression and PTEN loss synergistically promote prostate cancer progression." (PMID 29581856, 2018).
prostate carcinoma (continued). "Previous observations had prostate cancer divided in distinct molecular subgroups defined by TMPRSS2:ERG fusion and various genomic deletions." (PMID 29304771, 2018). "BET proteins enhance the oncogenic functions of major cancer drivers by elevating the expression of these drivers, such as c-Myc in multiple myeloma, androgen receptor (AR) and ETS-related gene (ERG) in prostate cancer, and TWIST in breast cancer." (PMID 30150556, 2018). "In prostate cancer cells harboring the TMPRSS2–ERG fusion, ERG expression is known to be highly induced by testosterone." (PMID 30291252, 2018). "ETS-related gene (ERG) is an oncogene that has, in the past decade, become closely linked with prostate cancer." (PMID 29342271, 2018). "Activation of WNT signaling by FZD4 was found in ERG [Erythroblast transformation-specific (ETS)-related gene]-positive prostate cancers." (PMID 29789460, 2018). "Nonetheless, our cellular and animal experiments support our notion that ERG-induced CITED2 promotes prostate cancer metastasis." (PMID 30291252, 2018). "In ERG fusion-positive prostate cancer (about 50% of cases) the androgen responsive TMPRSS2 gene fuses to the ETS family transcription factor ERG gene, increasing ERG protein expression." (PMID 29725501, 2018). "This indicates the importance of finding prostate neoplasm‐related miRNAs like miR‐145, whose target is proto‐oncogene ERG in prostate cancer." (PMID 28857494, 2018). "Analysis of RNA-seq data from 205 prostate cancer patients and 42 normal male individuals totally showed that the mRNA levels of both ERRα and ERG displayed significant higher expressions in tumor tissues as compared to that in normal prostatic tissues." (PMID 30042415, 2018). "Several studies demonstrated that ERG is highly and consistently expressed in many prostate cancer patients because of gene fusion with TMPRSS2, an androgen-dependent gene." (PMID 30237984, 2018). "In prostate cancer are after the TMPRSS2: ERG fusion, chromosomal deletions the most frequent type of genomic aberration." (PMID 29304771, 2018). "That PSCA expression was completely unrelated to TMPRSS2:ERG fusion further demonstrates that PSCA is not significantly affected by any of the hundreds of genes that are deregulated in ERG fusion positive prostate cancer." (PMID 29855276, 2018). "A recent study demonstrates that small molecules targeting the DNA-binding ETS domain of ERG can suppress its transcriptional activity and reverse transformed characteristics of prostate cancers aberrantly expressing ERG." (PMID 29581876, 2018). "Together, these results showed that up-regulation of both ERRα and ERG was positively correlated with the Gleason scores and metastasis in prostate cancer tissues." (PMID 30042415, 2018). "The TMPRSS2:ERG gene fusion is the most prevalent early driver gene activation in prostate cancers of European ancestry, while the fusion frequency is much lower in Africans and Asians." (PMID 30150711, 2018). "This gene fusion is the most common type found in prostate cancer and can be identified by overexpression of ERG in prostate carcinomas." (PMID 29342271, 2018). "In human cancers, chromosomal translocation, gene fusion, and amplification of ERG locus have been documented in acute myeloid leukemia, prostate cancer, and Ewing’s sarcoma." (PMID 29773901, 2018). "Earlier studies had provided evidence for distinct molecular subgroups of prostate cancer defined by TMPRSS2:ERG fusion and several genomic deletions." (PMID 29855276, 2018). "Compared to PC3 and DU145 with a lower level of ERG, three prostate cancer cell lines with high ERG expression had greater luciferase activity." (PMID 30291252, 2018).
prostate carcinoma (continued). "For example, BCR-ABL1 is a well-known fusion oncogene for chronic myeloid leukemia, and the TMPRSS2-ERG fusion product leads to over-expression of ERG and helps triggers prostate cancer." (PMID 29650026, 2018). "Note that bimodal genes occur in several biologically meaningful situations like fusion genes such as ERG in prostate cancer or hormone genes such as ESR1 in breast cancer." (PMID 30733688, 2018). "It is apparent that increased expressions of both ERRα and ERG would contribute to a more aggressive phenotype of prostate cancer." (PMID 30042415, 2018). "Because TMPRSS2:ERG fusion is the predominant genetic marker in prostate cancer we analyzed its relation to PSCA expression." (PMID 29855276, 2018). "We identified ERG as a transcription factor regulating expression of the CITED2 gene, which is specifically overexpressed in prostate cancer, and further clarified the ERG–CITED2 axis as the downstream pathway involved in prostate cancer." (PMID 30291252, 2018). "The protein is overexpressed in prostate cancer when the androgen-induced TMPRSS2 (transmembrane serine protease 2) gene fuses to the ERG gene." (PMID 30280090, 2018). "In a study of ERG and multi-phase prostate cancers (ADT treated cancers, CRPC, and mCRPC), expression was associated with loss of pTEN in prostatectomy and local CRPC patients." (PMID 29562686, 2018). "Analysis also showed that both ERRα and ERG manifested a positive expression correlation in prostate cancer." (PMID 30042415, 2018). "Recurrent gene fusions in the oncogenic transcription factor ERG, present in 40% to 50% of prostate cancers, define one such subclass, while a second distinct class, comprising 10% of prostate cancers, is defined by recurrent mutations in SPOP." (PMID 29202479, 2018). "Hereby, ERRα and ERG can synergistically regulate each other and form a reciprocal regulatory loop to promote the advanced growth of prostate cancer." (PMID 30042415, 2018). "ERG and CITED2 overexpression in the TMPRSS2–ERG gene fusion samples further support the ERG-driven overexpression of CITED2 in prostate cancer cells." (PMID 30291252, 2018). "Among these fusion genes, TMPRSS2:ERG (T:E) fusion is the most dominant rearrangement and prevalent in majority of prostate cancer patients (40–70%)." (PMID 30042415, 2018). "Nearly 50% of prostate cancers harbor gene fusions that lead to overexpression of the transcription factor ERG, while a mutually exclusive 10% of prostate cancers harbor recurrent mutations in the gene encoding the E3 ubiquitin ligase SPOP." (PMID 29202479, 2018). "We collected the ERG fusion status information from two prostate cancer genome studies and compared the relationship among ERG fusion, deletion and expression." (PMID 30150711, 2018). "ETV-4 has been reported to be associated with ETS-2 and ERG, and formed a complex integrated transcriptional network in PC3 cell nuclear extracts and prostate cancer tissues." (PMID 29915163, 2018). "ERG often co-overexpressed with FZD4 in prostate cancer, which led to cancer-promoting phenotypic effects, such as EMT and loss of cell adhesion." (PMID 29789460, 2018). "Prostate cancer cells positive for the fusion show increased ERG expression in response to androgens due to the TMPRSS2 promoter." (PMID 29693622, 2018). "Immunoblotting analysis in various prostate cancer cell lines showed an apparent correlation between ERG and CITED2 expressions." (PMID 30291252, 2018).
prostate carcinoma (continued). "Enforced expression of ERG results in morphological transformation of murine NIH3T3 cells, while silencing of ERG gene inhibits the proliferation and aggressiveness of prostate cancer cells, revealing its oncogenic potential." (PMID 29773901, 2018). "One confounding factor is that many prostate cancers express a TMPRSS2:ERG fusion gene whose expression is increased both by androgens and by vitamin D receptor (VDR) activation." (PMID 28591703, 2017). "Mechanistic studies of deregulated ERG in prostate cancer and other cancers continue to enhance its role in cancer biology and its utility as a biomarker and therapeutic target." (PMID 28439080, 2017). "Since ERG was shown to be an oncogenic protein, ERG target drugs became attractive agents for prostate cancer." (PMID 28264478, 2017). "First, AR can increase spatial association of the transmembrane protease, serine 2 (TMPRSS2) gene and ETS-related gene (ERG) and mediate TMPRSS2-ERG gene fusion, which is a clinical marker of prostate cancer." (PMID 29149895, 2017). "Significantly, the 3Mb deletion between ERG and TMPRSS2 on Ch21 was indicative of the TMPRSS2-ERG fusion product, a major molecular hallmark of prostate cancer." (PMID 29145505, 2017). "Chromosomal rearrangements between the androgen-regulated gene, TMPRSS2, and the oncogenic ETS transcription factor gene, ERG, occurs in approximately 30–50% of prostate cancers (PRAD)." (PMID 29299133, 2017). "Transmembrane protease serine 2 (TMPRSS2)-ERG fusion gene is one of the most common genomic alterations identified in about 50% of prostate cancer (urine or tissue)." (PMID 28061466, 2017). "The frequent ERG dependence of prognostic biomarkers in prostate cancer challenges the development and use of prognostic molecular test that are applicable to all patients." (PMID 28146062, 2017). "Earlier studies had demonstrated that the panel of chromosomal deletions occurring in prostate cancer is largely dependent on the ERG status." (PMID 27880722, 2017). "Prostate cancer with 3p13-14 FOXP1-SHQ1 loss nonetheless shows statistically independent enrichment of PTEN loss and ERG fusion, which themselves only show co-enrichment with each other in cancers without FOXP1-SHQ1 loss." (PMID 29057879, 2017). "Since then, several studies have focused on understanding the biological functions of ERG in prostate cancer initiation and progression." (PMID 28439080, 2017). "FZD4 (frizzled family receptor 4), a receptor for Wnt proteins, is a mediator of ERG oncogene–induced Wnt signaling and epithelial-to-mesenchymal transition in human prostate cancer cells." (PMID 28792525, 2017). "These novel insights will enhance the understanding of the mechanistic functions of ERG in prostate tumor biology and towards development of early targeted therapeutic strategies for prostate cancer." (PMID 28439080, 2017). "The most common TMPRSS2:ETS fusion is TMPRSS2:ERG; this fusion promotes growth in prostate cancer cells, in mouse prostate, and in xenograft models." (PMID 28591703, 2017). "ERG rearrangements and PTEN loss are concomitant events in prostate cancer (PrCa), and can cooperate in progression." (PMID 29088771, 2017). "More than half of all prostate cancers carry this gene fusion which links the androgen-regulated TMPRSS2 gene with the transcription factor ERG resulting in an androgen-dependent overexpression of the ERG transcription factor." (PMID 28415558, 2017). "One possible limitation of our study is the heterogeneity of TMPRSS2:ERG expression in prostate cancer patient tumors." (PMID 28591703, 2017). "Genetic rearrangements occurring early in prostate cancer development place ERG oncogene expression under the control of the androgen-regulated TMPRSS2 promoter to hijack cell behaviour." (PMID 28382513, 2017).
prostate carcinoma (continued). "Since, over half of the prostate cancer patients harbor TMPRSS2-ERG fusions, understanding the mechanistic role of ERG in mediating oncogenic transformation of prostate epithelium would facilitate better therapeutic strategies." (PMID 28439080, 2017). "It is less well known that even though the genomic translocation is highly specific for prostate cancer, ERG protein expression is seen in a variety of other tumors, too." (PMID 28555048, 2017). "We then demonstrated VPC-18005 reduced migration and invasion rates of ERG expressing prostate cancer cells, and reduced metastasis in a zebrafish xenograft model." (PMID 28465491, 2017). "The relationship between GGH expression, androgen receptor (AR) expression, and ERG activation was analyzed because of the central role of AR for prostate cancer, and because ERG activation is the most frequent molecular alteration in this tumors." (PMID 28146062, 2017). "Our study is the first to explore VDR action in prostate cancer using next generation RNA sequencing of the TMPRSS2:ERG positive VCaP cell line." (PMID 28591703, 2017). "Chromosomal deletions represent the most frequent genomic changes in prostate cancer next to TMPRSS2:ERG fusion." (PMID 28747165, 2017). "Taken together, new insights from this report enhance the biochemical and biological role of ERG in early stages of prostate cancer development and its utility both as biomarker and therapeutic target." (PMID 28439080, 2017). "Since the anti-tumor efficacy of YK-4-279 in Ewing’s sarcoma was demonstrated in 2009, ERG/ETV1-mediated prostate cancer and EWS-FLI1-induced leukemia have been verified as additional target diseases." (PMID 29212266, 2017). "ERG is not normally transcriptionally controlled by androgens, but gene fusions can place ERG under transcriptional control by the androgen-regulated TMPRSS2 gene on the transition between prostatic epithelial neoplasia to prostate carcinoma." (PMID 28382513, 2017). "In summary, our study demonstrates that the prognostic impact of YB-1 in prostate cancer depends on the ERG fusion status and on the intracellular localization of the protein." (PMID 28515422, 2017). "The potential role of ERG as a cancer driver and the high incidence of the TMPRSS2-ERG gene fusion in prostate cancer have catapulted this protein into the forefront of new targets for therapeutic intervention." (PMID 27626314, 2016). "The discovery and functional validation of recurrent gene fusions of 5 Ets factor genes (ETV1, ETV4, ETV5, ERG, Fli1) in prostate cancer highlights the relevance of Ets transcription factors as oncogenes in prostate cancer." (PMID 26885618, 2016). "Out of 369 miRNAs, the average expression levels of four miRNAs including miR-200a, miR-200b, miR-429, and miR-205 were significantly higher in ERG-positive human prostate cancer samples." (PMID 27191272, 2016). "ERG modulates AR signaling in VCaP cells and the murine prostate gland, and therefore contributes to prostate cancer progression." (PMID 27191272, 2016). "In summary, our results indicate that miRNAs are important components of the ERG transcriptional network in human prostate cancer." (PMID 27191272, 2016). "Analysis of prostate cancer samples also showed that miR-221 is down-regulated in patients with TMPRSS2-ERG gene fusion-positive tumours compared to ERG fusion negative samples." (PMID 27208692, 2016). "Transactivation of the IGF1R gene by oncogene ERG constitutes a key event in prostate cancer development." (PMID 27285981, 2016). "One exciting finding of our study is that ERG directly up-regulates the tumor suppressive miR-200b subfamily of miRNAs in prostate cancer." (PMID 27191272, 2016). "Thirdly, the TMPRSS2/ERG fusion prevalence is significantly different in prostate cancers from different ethnic groups." (PMID 27191272, 2016).